IL1B (interleukin 1 beta)
Diseases named in the same sentence as IL1B in open-access papers (continued):
Sharing a sentence is not in itself a finding about the gene and the disease.
Sepsis (continued). "A similar phenotype was observed in a model of sepsis, where whole-body PTP1B deletion not only improved survival rate in response to septic shock, but decreased cardiac dysfunction and the expression of pro-inflammatory markers such as IL1β, ICAM-1, VCAM-1, COX-2 and iNOS." (PMID 28899902, 2017). "In addition to attenuating the abrupt release of pro-inflammatory cytokines, including TNF-α, IL-1β and IL-6, treatment with chlorogenic acid enhanced serum Th1 cytokines during the late phase of sepsis without affecting Th2 cytokine release." (PMID 26063084, 2015). "Therapeutic effects of CORM-2 on sepsis-induced AKI were assessed by measuring serum creatinine (Scr) and blood urea nitrogen (BUN), kidney histology scores, apoptotic cell scores, oxidative stress, levels of cytokines TNF-α and IL-1β, and NLRP3 inflammasome expression." (PMID 26334271, 2015). "No IL-1β increase during sepsis was detected in other studies." (PMID 25407756, 2014). "We speculate that proinflammatory cytokines such as TNF-α, IL-1β, and IL-6 were released in the early stage of ALI challenge; in other studies, IL-6 was considered a particularly useful marker for prediction of the severity of sepsis." (PMID 25022445, 2014). "The study of proinflammatory cytokines IL-6, TNF-α, IL-1β, and IL-8 and anti-inflammatory cytokines IL-10 and TGF-β as reliable biomarkers of neonatal infection has been shown to be potentially useful for early sepsis diagnosis and to predict the severity of disease at early stages of the infection." (PMID 25614712, 2014). "It has been found that α2-adrenoreceptor agonist might attenuate the increase in plasma level of IL-1β, TNF-α and improve survival successfully after caecal ligation and puncture (CLP)-induced sepsis, and reduce the incidence of sepsis-induced AKI by decreasing TNF-α and MCP-1." (PMID 23759023, 2013). "Interestingly, increase of TNF-α and IL-1β concentrations, but not IL-10 in plasma after administration of nociceptin has been also reported in a rat model with sepsis." (PMID 24066107, 2013). "Finally, urate crystals, which specifically induce the NLPR3 inflammasome activation, induced significant IL-1β production in healthy controls but not in patients with sepsis." (PMID 21244670, 2011). "Also, the chemokines, CCL-2, CXCL-2, and cytokines, IL-1β and IL-6, were not affected by NK-2R blocking in sepsis." (PMID 21188216, 2010). "NLRP3 inflammasome, a typical Nod-like receptor, is also an important PRR in sepsis, and it has been reported that exosomes released from LPS-treated macrophages could induce NLRP3 inflammasome and caspase-1 activates and induces the release of the proinflammatory factor IL-1β." (PMID 35326456, 2022). "The results showed that IL-1β, IL-6, and TNF-α contents of model group increased markedly vs. control and interference groups, suggesting that IL-17RA-1 might promote the secretion of proinflammatory factors by THP-1-M1 cells, contributing to the development of sepsis." (PMID 36274974, 2022). "Baicalin could significantly reduce IL-1β in the sera of bacterial infected mice and could inhibit NLRP3 inflammasome activation through augmenting PKA signaling, thereby improving mouse survival in bacterial sepsis and could reduce the level of LPS, TNF-α, and IL-6 in the blood of sepsis mice." (PMID 34938184, 2021). "Therefore, the effect of CaD to decrease CD14 and TLR4 expression could offer one mechanism to explain why CaD inhibits NF-κB and suppresses the release of downstream NF-κB activation products—TNFα, IL-1β, IL-6, and MCP-1 in animal models of sepsis and diabetic nephropathy and retinopathy." (PMID 34829669, 2021). "Therefore, we studied the occurrence of pyroptosis and autophagy as well as the release of IL-1β and IL-18 after LPS stimulation of HUVECs and macrophages with RAPA, in order to understand whether the latter can be used in the earliest stages of sepsis to block inflammatory cytokine storm." (PMID 32851082, 2020).
Sepsis (continued). "Based on these previous findings, the hypothesis that TLR4 signaling is required to trigger the release of IL-1β under conditions of systemic inflammation appears quite plausible, although TLR4 on DCs are known to regulate inflammatory neutrophils or spleen DCs during sepsis." (PMID 31323786, 2019). "Nevertheless neither TNF or IL-1β have emerged as reliable biomarker for hyperinflammation in sepsis patients, potentially because they are elevated only for a very short period of time in the initial phase of sepsis, when patients may not yet have been admitted to the ICU." (PMID 30233566, 2018). "Furthermore, a recent study showed that polymicrobial sepsis greatly induced generation of inflammatory mediators in hearts, and CMs isolated from septic rodents spontaneously secreted cytokines and chemokines (IL-6, TNF-α, IL-1β, MIP-1α, MIP-2, MCP-1, KC, and IL-10) in a time-dependent manner." (PMID 23233853, 2012). "Furthermore, plasma levels of IL-1β, IL-6, MIP-2, and MIP-1α were obviously down-regulated in C5aR knockout mice when compared with wild type littermates, suggesting that the harmful effects of C5aR during sepsis might result from C5a-mediated cytokine storm." (PMID 23233853, 2012). "However, anti-IL-1β treatment does not increase survival in patients with severe sepsis." (PMID 21939530, 2011). "○Enhanced antibacterial and antibiofilm activity against Gram‐positive and negative bacteria.○Reduction in the levels of TNF‐α, IL‐1β and IL‐6 in CLP model.○Effective reduction of sepsis‐induced multiple organ damage.○Improved survival rates." (PMID 40599085, 2025). "While plasma inflammatory cytokine levels also rise during endotoxemia, such as sepsis, it has been reported that TNF-α and IL-1β do not increase in response to exercise-induced cytokine production, a pattern similarly observed in this study." (PMID 41154623, 2025). "AKI patients showed increases in sepsis-related organ failure assessment (SOFA) score, BUN, Scr, TNFα and IL-1β levels compared to non-AKI patients." (PMID 41406481, 2025). "IL-8 and IL-18 on day 1 (r = 0.26 and r = 0.24) and IL-1β on day 5 (r = −0.45) showed correlation in the non-MASLD group, but not in the MASLD group, where TGF-β1 negatively correlated with sepsis severity on day 5 (r = −0.22)." (PMID 40076848, 2025). "We found higher levels of IL-1β, C3AR1, and IL1R1 transcripts in patients with sepsis and a positive correlation between expression levels of IL-1β and C3AR1 in sepsis patients but not healthy controls." (PMID 38236896, 2024). "Of note, IL-1b, IL-6, IL-10, TNF-a, and suPAR did not significantly change during the first week of sepsis (p > 0.05)." (PMID 39272772, 2024). "On the fifth day of modeling, the levels of IL-1β, IL-6, and TNF-α in the mouse serum were not significantly different between the sepsis and sepsis-AW group but were significantly higher than those in the normal control group." (PMID 36016684, 2022). "A retrospective study evaluated a broad panel of cytokines and found IL-1β, IL-6, IL-8, MCP-1, IL-10, and plasminogen activator inhibitor 1 (PAI-1) levels were increased in the acute phase of sepsis in both critically and non-critically ill patients." (PMID 34991675, 2022). "When nonsurvivors of the two groups were compared, the levels of serum IL-1β, IL-2R, IL-6, IL-8, and TNF-α were also lower in SARS-CoV-2 sepsis nonsurvivors." (PMID 33329592, 2020). "Our results indicate that simvastatin treatment has an important negative immunomodulatory effect in sepsis since it was able to lower the levels of IL-6, TNF-α, IL-1β, and MIF in the peritoneal cavity in our model." (PMID 33110395, 2020). "Narciclasine treatment showed significant reduction of inflammatory cytokines (TNF-α, IL-6, IL-1β and IFN-γ) in liver homogenates compared to the sepsis group without treatment." (PMID 32076015, 2020).
Sepsis (continued). "Treatment with narciclasine significantly reduced the levels of inflammatory cytokines TNF-α, IL-6, IL-1β and IFN-γ in lung homogenates when compared to the sepsis group without treatment." (PMID 32076015, 2020). "Normal release of IL-1β and ASC-speck formation was found in non-compromised NLRP3 septic patients during the course of the first 5 days of sepsis." (PMID 31221993, 2019). "Postmortem course of Interleukin-1β (IL-1β), sIL-2R, and LBP has been evaluated in septic and non-septic fatalities, showing that sIL-2R and LBP can be useful in diagnosis of sepsis in forensic autopsy practice." (PMID 31661804, 2019). "As anti-inflammatory treatments in humans with antibodies to TNF-α or IL1-β resulted disappointing, cytokine modulation approaches were discouraged and neutralization of IFN-β has not been pursued for sepsis treatment." (PMID 28533774, 2017). "The other cytokines in our study (IL-1β, TNF-α, IL-12/23p40, IL-21, IL-17, G-CSF, and GM-CSF) do not appear to be useful markers for clinical decisions regarding sepsis." (PMID 28769538, 2017). "Sepsis induced serious inflammatory pathological injuries and increased potent pro-inflammatory cytokines TNF-α and IL-1β, which were suppressed by CORM-2, but not iCORM-2, intervention." (PMID 27144520, 2016). "At the time of diagnosis, IL-1β, IL-6, IL-8, and TNF-α levels of culture-proven sepsis and culture-negative sepsis were significantly higher than levels at the seventh day after antibiotic treatment." (PMID 18274637, 2007). "Attime of diagnosis, serum IL-1β, IL-6, IL-8, and TNF-α levels of culture-provensepsis and culture-negative sepsis were significantly higher than levels atseventh day after antibiotic treatment (P<.05)." (PMID 18274637, 2007). "Previous studies have shown that IL-1β, but not TNF-α or IL-6, is the exclusive cytokine within the CNS that has been verified to remain elevated for up to 70 days in rats survived neonatal sepsis but subsequently developed cognitive impairment." (PMID 38665289, 2024). "During sepsis (resulting from severe infection mostly with Gram-negative bacteria), platelets become overactivated and release PEVs containing numerous molecules and DAMPs, such as HMGB1, proinflammatory cytokines (IL-1β, TNF-α, IL-6) and chemokines (MCP-1)." (PMID 37559007, 2023). "Finally, omentin-1 at sepsis onset presented a significant positive correlation only with CRP, but not with procalcitonin, IL-1β, IL-6, IL-10, or suPAR." (PMID 37241065, 2023). "However, data regarding the therapeutic effects of triple cytokine (TNF-α, IL-1β, and IL-6) inhibitions versus single cytokine (TNF-α) inhibition against sepsis remain lacking." (PMID 35337084, 2022). "Also, we did not observe significant changes in IL-1β and IL-18 levels between wild-type and Casp1−/− mice administered a high dose of HNP-1 after sepsis onset." (PMID 35935811, 2022). "The main difference between IL-6 response in sepsis and training is that in sepsis, there is a marked increase in circulating levels of tumor necrosis factor alpha (TNF-α) and IL-1β, prior to the increase in IL-6, which does not happen after acute or chronic physical exercise." (PMID 32765291, 2020). "However, in monocytes from NLRP3 compromised septic patients, P2X7 receptor expression did not correlated with IL-1β release, suggesting an alternative role for P2X7 receptors in sepsis." (PMID 31221993, 2019). "TNF mediates inflammation in a classic “sepsis” cascade in tissues—in this pathway LPS from gram negative bacteria activates TNF release from cells, and then TNF stimulates production of IL-1b, IL-6, and IL-8, leading to neutrophil attraction into sites of infection." (PMID 30828428, 2018). "Although circulating IL-1β and IFN-γ are not the only factors that induce sepsis, our findings suggest that regular exercise during pregnancy is a potential predictor of the onset of systemic inflammation and development of sepsis in offspring." (PMID 29928698, 2018).
Sepsis (continued). "However, in the lipopolysaccharide (LPS) model of sepsis, while overexpression of PPAR-γ in cardiomyocyte prevents septic cardiac dysfunction, cardiac mRNA levels of interleukin 1β (IL-1β), IL-6, and TNF-α are not reduced." (PMID 28845215, 2017). "Interestingly, cytokines that are most commonly employed in experimental models of inflammation and/or sepsis (TNF-α, IL-1β, and IFN-γ) were not significantly increased in severe sepsis plasma obtained within 24 hours of ICU admission." (PMID 25882865, 2015). "Moreover, serum levels of IL-1β, IL-2, IL-4, IL-10, IL-17, IFN-α, IFN-β and IFN-γ were not elevated in severe sepsis survivors compared with sham-operated control mice (data not shown)." (PMID 23808943, 2013). "However, IL-1β expression was not significantly altered between vehicle and DHEA treatment in the sepsis groups at any observation point (48 hours and 96 hours) in the tissue types investigated (lung and liver)." (PMID 19594900, 2009). "When incubated for 6 hours without extrinsic stimuli, whole blood from sepsis patients, which already contained greater inflammatory cytokine concentrations than that of healthy volunteers, showed a significant further increase of supernatant TNF, IL-6, IL-8, IL-1α, and IL-1β concentrations." (PMID 37869001, 2023). "Attime of diagnosis, serum IL-1β, IL-6, IL-8, and TNF-α levels of culture-provensepsis were significantly higher than those of the control groups (P<.05);but only serum IL-8 levels of culture-proven sepsis was significantly higherthan culture-negative sepsis (P<.05)." (PMID 18274637, 2007). "However, the most remarkable is the increase of IL-1β, IL-6, IFN-γ, and TNF-α expression in the hippocampus and IL-6, IL-17, and IFN-γ in the PFC 10 days after CLP surgery when the blood culture was negative, and the animals presented a full recovery from sepsis." (PMID 35606817, 2022). "However, Cobalt alloy particle induced inflammatory responses as determined by IL-1β and TNF-α secretion in vitro were not as pro-inflammatory relative to TLR4 PAMP agonist despite high levels of PAMP agonist (LPS) used at levels corresponding to sepsis (>500pg/mL)." (PMID 27467577, 2016).
COVID-19 (1,334 papers, 2020 to 2026). A disease caused by infection with severe acute respiratory syndrome coronavirus 2. "Co-infection also triggered robust increases in IFN-γ and IL-1β, whereas malaria alone was associated with higher IL-6, IL-4, and IL-10, and COVID-19 alone was associated with elevated IL-2 and TNF-α." (PMID 41758897, 2026). "Among the 19 intersecting targets identified between G. pentaphyllum compounds and COVID-19-associated genes, several key nodes—IL1B, IL6, TNF, ACE, and REN—emerged as central in both the protein–protein interaction and compound–target networks." (PMID 41471341, 2025). "IL-1β is a key pro-inflammatory cytokine involved in early immune response and has been implicated in acute myocarditis and systemic inflammation during COVID-19." (PMID 41472298, 2025). "A recurring feature of lung monocytes in fatal cases of COVID-19 is the expression of IL-1β, and inflammasome activation has been associated with the non-productive infection of monocytes." (PMID 40920821, 2025). "Six genes, including TNF, CXCL8, IL-6, IL-1β, IL-2, and IL-10, were associated with three major signaling pathways: the COVID-19 adverse outcome pathway, an overview of pro-inflammatory and pro-fibrotic mediators, and the interleukin-10 signaling pathway." (PMID 40166075, 2025). "Studies have indicated a strong association between elevated levels of IL-1β and severe outcomes in COVID-19, including the development of pulmonary fibrosis and the need for invasive mechanical ventilation." (PMID 40506975, 2025). "A study showed that the T allele of IL1B +3953C > T provides protection against severe COVID-19, while the CT genotype increases the risk of severity." (PMID 40506975, 2025). "Inflammasome and pyroptosis signalling have been implicated in the pathogenesis of COVID-19 because of their known link to the release of bio-active IL-1β and IL-18." (PMID 40016339, 2025). "COVID-19 is also associated with high levels of proinflammatory cytokines such as interleukin-6 (IL-6), IL-1B, IL-18, and granulocyte-macrophage colony-stimulating factor, a state commonly referred to as “cytokine storm”." (PMID 40066309, 2025). "During SARS-CoV-2 infection, activation of the NOD-like receptor family pyrin domain-containing 3 (NLRP3) inflammasome pathway is thought to contribute to the release of bioactive IL-1β and IL-18, cytokines associated with severe COVID-19." (PMID 40016339, 2025). "Prior research consistently supports an association between elevated IL-1β levels and increased mortality in COVID-19." (PMID 41217548, 2025). "It was shown that miR-142-3p is part of a detrimental regulatory axis with proinflammatory cytokines IL-1β and IL-6 in COVID-19 patients, inducing a response associated with respiratory failure and death." (PMID 39311385, 2024). "interleukin-6 (IL-6), IL-10, tumor necrosis factor (TNF)-α, IL-1β, IL-4, IL-8 and IL-17 are associated with increased severity as well as mortality in COVID-19 patients." (PMID 38544825, 2024). "Recent evidence has indicated that the prolonged presence of certain cytokines such as TNFα, IL-16 and IL-1β is associated with the persistent symptoms of disease in COVID-19 known as post-acute sequelae or long COVID-19." (PMID 38400083, 2024). "The release of excessive levels of transforming growth factor (TGF), interferon (IFN), interleukin (IL)-1b, IL-6, IL-12, IL-18, and IL-33 is associated with COVID-19 causing changes in platelet indices, according to evidence in the literature." (PMID 39006704, 2024). "Thereby, the main perspective of our work was to study the association of three substantial gene polymorphisms (IL-6R rs12083537, IL-1β rs16944, and IL-1β rs1143634) with COVID-19 severity among Egyptian patients." (PMID 39452786, 2024). "Elevated IL-1β, IL-6, IL-8, IL-10, and IL-17 in plasma is associated with disease severity in COVID-19 patients." (PMID 39739157, 2024).